ACE (angiotensin I converting enzyme)
Diseases named in the same sentence as ACE in open-access papers (continued):
Sharing a sentence is not in itself a finding about the gene and the disease.
sarcoidosis (316 papers, 2005 to 2026). Sarcoidosis is a multisystemic disorder of unknown cause characterized by the formation of immune granulomas in involved organs. "The peripheral eosinophilia and elevated ACE level observed in our patient are consistent with sarcoidosis, with the latter serving as a useful diagnostic marker." (PMID 40585695, 2025). "Angiotensin-converting enzyme (ACE) and soluble interleukin-2 receptor (sIL-2R) are associated with lung function in sarcoidosis but of limited practical use." (PMID 39881845, 2025). "Serum angiotensin-converting enzyme (ACE) has long been associated with sarcoidosis diagnosis, monitoring and activity." (PMID 40002701, 2025). "Although ACE levels increase in 75% of patients with untreated sarcoidosis, the biomarker's sensitivity is low and its specificity is insufficient, resulting in a low diagnostic utility for serum ACE values." (PMID 40502903, 2025). "In this case, the combination of histopathological findings, elevated ACE levels, and rheumatological evaluation fulfilled the diagnostic criteria for sarcoidosis." (PMID 40756099, 2025). "To conclude, findings from this study indicate that severe SAHC in Swedish sarcoidosis patients is associated with sun exposure, elevated s-ACE and HLA-DRB1*04." (PMID 39939699, 2025). "The angiotensin-converting enzyme (ACE) has been used as a diagnostic tool, with elevated levels indicating active sarcoidosis." (PMID 41374442, 2025). "Although elevated ACE levels are known to support the diagnosis of sarcoidosis, their diagnostic utility is limited by variable sensitivity and specificity." (PMID 41200618, 2025). "Serum angiotensin-converting enzyme (ACE) levels are elevated in 75% of untreated sarcoidosis patients, but their diagnostic utility is limited due to poor sensitivity and insufficient specificity, with false-positive rates." (PMID 39301395, 2024). "Lab tests used in the diagnostic work-up and follow-up of patients with sarcoidosis are angiotensin converting enzyme (ACE) and serum-soluble interleukin-2 receptor (sIL2R)." (PMID 39445489, 2024). "ACE insertion/deletion polymorphism also influences sACE activity, yielding variable specificity in sarcoidosis patients." (PMID 38611622, 2024). "In one study, all (n = 9) pediatric patients diagnosed with sarcoidosis-associated uveitis had elevated ACE levels." (PMID 37721575, 2023). "The serum ACE activity is affected by the site of sarcoidosis lesions and the ACE gene I/D polymorphism." (PMID 37868968, 2023). "Some studies find associations between ACE concentration and granuloma burden and radiological presentation of sarcoidosis." (PMID 37510860, 2023). "Secondly, it has been reported that the ACE I/D polymorphism is associated with susceptibility to sarcoidosis in European and East Asian populations." (PMID 36291609, 2022). "Cigarette smoking is not only associated with an increase in sACE activity in sarcoidosis patients, but it also increases the concentration of ACE in alveolar fluid with tobacco use." (PMID 36291609, 2022). "Although angiotensin-converting enzyme (ACE) and soluble interleukin 2 receptor (sIL-2R) are traditionally used for the diagnosis of sarcoidosis, specific diagnostic markers remain to be determined." (PMID 35663496, 2022). "Previous studies have shown that serum levels of ACE and sIL-2R have a tendency to increase in patients with active sarcoidosis and are associated with the number of involved organs." (PMID 35663496, 2022). "After excluding explanatory variables with p > 0.05, multivariate logistic regression analysis revealed that U-ATX, ACE and sIL-2R were also independently associated with the activity of sarcoidosis." (PMID 35288647, 2022). "Univariate logistic regression analysis with 5 variables revealed that U-ATX, ACE and sIL-2R were associated with the activity of sarcoidosis." (PMID 35288647, 2022).
sarcoidosis (continued). "Increased serum ACE activity has been reported, particularly in uveitis associated with sarcoidosis, as well as infectious uveitis such as recurrent toxoplasmic and toxocaral iridocyclitis, chorioretinitis, and Vogt–Koyanagi–Harada's diseases." (PMID 32318310, 2020). "In sarcoidosis the excess of ACE is possibly synthesized by granuloma cells, which causes an increase of this marker in the blood of patients." (PMID 31974463, 2020). "One of these is angiotensin-converting enzyme (ACE) which has been extensively investigated since it was first reported to be associated with sarcoidosis in 1975 by Lieberman." (PMID 32111204, 2020). "Elevation of angiotensin-converting enzyme (ACE) levels in sarcoidosis appears to be associated with the active disease process." (PMID 30459928, 2018). "There has been controversy concerning the role of serum ACE as a diagnostic and activity marker for sarcoidosis." (PMID 30154391, 2018). "An ACE Insertion/Deletion polymorphism has been tested for association with the risk of sarcoidosis." (PMID 28253271, 2017). "Increased serum ACE activity has been reported especially in uveitis associated with sarcoidosis, and also infectious uveitis such as recurrent toxoplasmic and toxocaral iridocyclitis and choroioretinitis." (PMID 26879979, 2016). "Epithelioid cells of the granulomata produce angiotensin converting enzyme (ACE), a controversial biomarker of sarcoidosis that is often elevated, but lacks diagnostic specificity and sensitivity." (PMID 27832822, 2016). "High levels of plasmatic angiotensin-converting enzyme (ACE) in the presence of an RCM suggests the existence of underlying sarcoidosis." (PMID 24826302, 2013). "Sarcoidosis-associated markers (neopterin, ACE, IL-2 receptor) were elevated." (PMID 42305552, 2026). "It has also been proposed that ACE might serve as a diagnostic tool and a gauge for disease activity in sarcoidosis, since it is secreted from activated macrophages within sarcoid granulomas." (PMID 39365404, 2024). "Although the ACE enzymes were normal, we believe the variant in the ACE gene could also play a role in the diagnosis of sarcoidosis in our patient." (PMID 39483609, 2024). "It is speculated that the homozygous D allele of ACE may contribute to the autoimmune susceptibility of sarcoidosis through the elevated serum ACE level." (PMID 37868968, 2023). "About potential laboratory tests of diagnostic utility for sarcoidosis, serum levels of angiotensin-converting enzyme (ACE) and soluble IL-2 receptor (sIL-2R), although raised in a substantial proportion of patients with sarcoidosis, showed a low diagnostic value." (PMID 34830565, 2021). "Usually, the detection of ACE levels is also used in the diagnostic and monitoring processes of sarcoidosis patients, but the role of this biomarker is contradictory in real life; however, a correlation between ACE levels and the dynamics of the granuloma burden has been shown." (PMID 34830565, 2021). "Several biomarkers are determined in the standard diagnostic work-up and follow-up of patients with sarcoidosis, like serum angiotensin-converting enzyme (ACE) and soluble interleukin 2 receptor (sIL-2R) in serum, as well as lymphocytes and CD4+/CD8+ ratio in bronchoalveolar lavage." (PMID 31197630, 2019). "Furthermore, the ACE levels had very good diagnostic value in patients with active sarcoidosis (sensitivity: 0.85; specificity: 0.718)." (PMID 30154391, 2018). "Sarcoidosis is often associated with elevated serum Angiotensin-converting enzyme (ACE) levels." (PMID 28253271, 2017). "Due to very high elevation of blood ACE level (much higher that in the case of sarcoidosis or Gaucher diseases, comparable with blood ACE levels characteristic for ACE mutations the hypothesis of a familial elevation of circulating ACE level was considered." (PMID 23560051, 2013). "Additionally, we propose that the variant in the ACE gene may contribute to the pathogenesis and diagnosis of sarcoidosis." (PMID 39483609, 2024).
sarcoidosis (continued). "However, the specificity of serum lysozyme level has been reported to be less for sarcoidosis than serum ACE level, and it has been considered that the diagnostic value of serum lysozyme for sarcoidosis might be limited." (PMID 26879979, 2016). "In this study, we investigated the relationship between FDG-PET/CT metabolic parameters and serum ACE and calcium levels as surrogate indicators of inflammatory metabolic intensity in patients with biopsy-proven sarcoidosis." (PMID 41594254, 2026). "Serum ACE levels are elevated in many patients with sarcoidosis and were initially thought to parallel disease activity." (PMID 41594254, 2026). "We have compared the levels of ACE and chitotriosidase with the levels of SUVmax values in patients with sarcoidosis." (PMID 40386527, 2025). "ACE is often used as a diagnostic tool in sarcoidosis, and when hypercalcemia is present in patients with sarcoidosis, elevated ACE levels are found in nearly all patients." (PMID 40689241, 2025). "This case highlights a diagnostic challenge where a patient with persistent hypercalcaemia and acute kidney injury was later confirmed to have sarcoidosis with inconclusive early findings and a low serum ACE level." (PMID 40709165, 2025). "Between 30–80% of sarcoidosis patients have increased ACE levels, sensitivity ranges between 22 and 86%, and specificity between 54 and 95%." (PMID 40386527, 2025). "Serum angiotensin‐converting enzyme (ACE) concentrations are elevated in a substantial proportion of those with active sarcoidosis‐reported in up to 60%–80%‐but are less commonly raised in chronic cases or in individuals receiving corticosteroid therapy." (PMID 41383541, 2025). "The patient’s severe hypercalcemia, generalized lymphadenopathy, elevated angiotensin-converting enzyme (ACE) levels, and 1,25-dihydroxy vitamin D were key findings suggesting sarcoidosis." (PMID 40018507, 2025). "Sarcoidosis tends to be bilateral and systemic with elevated ACE levels, whereas tuberculosis often presents with basal meningeal enhancement and positive interferon-gamma release assays (IGRAs)." (PMID 40985429, 2025). "Finally, laboratory markers such as serum ACE may support disease activity assessment, but their diagnostic accuracy is limited by variable sensitivity and specificity and by elevations in conditions other than sarcoidosis." (PMID 41487849, 2025). "Antisaccharomyces cerevisiae antibodies are elevated in CD, whereas sarcoidosis has hypercalcemia and elevated 1,25 Vitamin D and ACE levels; these are unreliable for concrete differentiation as many cases of sarcoid have normal 1,25 Vitamin D and ACE levels." (PMID 41209849, 2025). "Clinicians frequently rely on the presence of extraintestinal sarcoidosis, levels of angiotensin-converting enzyme (ACE), and their index of suspicion, which can introduce a high risk of bias." (PMID 41209849, 2025). "Due to the wide range of sensitivity and specificity and the influence of ACE inhibitors, the levels of ACE in diagnostics and response to treatment of sarcoidosis should be carefully analysed, as it can lead to false positive and negative results." (PMID 40386527, 2025). "Elevated serum angiotensin-converting enzyme (ACE) levels are often used as a supportive biomarker in the diagnosis of sarcoidosis." (PMID 41226948, 2025). "High serum levels of ACE and 1, 25-dihydroxyvitamin D also indicated the presence of active sarcoidosis." (PMID 39822610, 2025). "The history of prolonged fever, elevated inflammatory markers, anemia, acute kidney injury, hypercalcemia, bilateral hilar prominence, mediastinal lymphadenopathy, and raised ACE levels prompted consideration of sarcoidosis." (PMID 40988789, 2025). "The laboratory findings revealed elevated creatinine and calcium levels, suppressed intact parathyroid hormone (iPTH) and increased calcitriol and angiotensin-converting enzyme (ACE) levels, raising suspicion of sarcoidosis." (PMID 40520830, 2025).
sarcoidosis (continued). "Serological findings contributed to identifying rheumatoid meningitis with positive anti-CCP antibody (PT-8) and sarcoidosis with elevated serum angiotensin converting enzyme (ACE) levels (PT-3)." (PMID 40342619, 2025). "Serum eHSP90α level in sarcoidosis patients was significantly correlated with several biomarkers of sarcoidosis, including ACE, sIL-2R, and lysozyme." (PMID 39881845, 2025). "In sarcoidosis, serum concentrations of sIL-2R and ACE have been identified as biomarkers for sarcoidosis in patients with uveitis." (PMID 39249513, 2025). "Based on the elevated IL-2 receptor and ACE levels in conjunction with the imaging findings, malignant lymphoma and sarcoidosis were considered in the differential diagnosis." (PMID 41210040, 2025). "The clinical utility of serum ACE activity in sarcoidosis is also limited because of poor sensitivity and specificity, with high ACE activity occurring in up to 75% of cases." (PMID 39906901, 2025). "The link between ACE and immunity was first suggested in 1975, when elevated serum ACE levels were found in most patients with active sarcoidosis." (PMID 40722848, 2025). "Non-caseating granulomas, pulmonary involvement (mediastinal lymphadenopathy), and elevated serum angiotensin-converting enzyme (ACE) levels can help distinguish sarcoidosis from TINU." (PMID 40002713, 2025). "Previous studies have shown that elevated serum ACE levels have reasonable specificity (83–99%), but low sensitivity (41–100%), and are found in 30–80% of sarcoidosis patients." (PMID 39768579, 2024). "Although the number of patients with sarcoidosis was relatively small, these were compared to a relatively large number of control patients in which ACE levels were also assessed." (PMID 39768579, 2024). "Serum angiotensin-converting enzyme (ACE) levels are widely used in the clinic for the diagnosis and monitoring of sarcoidosis, despite accruing evidence of disutility." (PMID 39768579, 2024). "He developed uveitis and was found to have a variant in the angiotensin-converting enzyme (ACE) gene, which led to the diagnosis of sarcoidosis." (PMID 39483609, 2024). "This small sample size is in line with a meta-analysis showing that ACE levels have moderate performance in predicting sarcoidosis disease activity." (PMID 39768579, 2024). "Serum angiotensin-converting enzyme (ACE) is a reliable marker of sarcoidosis, which can manifest with uveitis in 30–70% of cases." (PMID 38337852, 2024). "Our data indicate that while ACE levels have a sensitivity of 63.5% for sarcoidosis, consistent with other studies, their specificity is considerably lower at 59.5%, compared to the 93% specificity reported in a meta-analysis." (PMID 39768579, 2024). "In an Italian study involving 694 sarcoidosis patients, chitotriosidase activity and ACE concentrations show a direct correlation." (PMID 38611622, 2024). "Prediction of sIL-2R levels based on serum ACE levels provides a non-invasive approach to assessing lung function and disease activity in sarcoidosis patients." (PMID 39896373, 2024). "In this study, we aimed to evaluate the utility of serum ACE levels in diagnosing sarcoidosis and monitoring its clinical course." (PMID 39768579, 2024). "ACE levels were found to be elevated in 68.3% of patients having subcutaneous sarcoidosis, which is also noted in the current case study." (PMID 38978890, 2024). "Background/Objectives: ACE (angiotensin-converting enzyme) is considered a serological marker of sarcoidosis as elevated levels have been reported in 30–80% of patients." (PMID 39768579, 2024). "In healthy individuals, blood ACE levels are very stable throughout their life span, whereas in granulomatous diseases (e.g., sarcoidosis) and Gaucher’s disease, blood ACE activity is significantly increased." (PMID 38255267, 2024). "Elevated ACE levels had a sensitivity of 63.5% for the diagnosis of sarcoidosis in our cohort, with a specificity of 59.5%." (PMID 39768579, 2024).
sarcoidosis (continued). "A 2019 study demonstrated that serum sIL-2R exhibits high sensitivity and specificity compared to angiotensin-converting enzyme (ACE) in diagnosing sarcoidosis." (PMID 38611622, 2024). "Elevated serum angiotensin-converting enzyme (ACE) and lysozyme have been suggested as tools for the diagnosis of sarcoidosis." (PMID 38787250, 2024). "In sarcoidosis, elevated ACE levels and granulomatous inflammation align with the pulmonary damage seen in COVID-19, where SARS-CoV-2 uses ACE2 to enter cells." (PMID 39852350, 2024). "ACE can be secreted by monocytes, macrophages, and epithelioid cells and is involved in the pathogenesis of sarcoidosis as an important modulator of granuloma formation and correlates with the presence of granulomas and radiologic stages II and III." (PMID 39598118, 2024). "Elevated ACE levels were most commonly encountered among patients with sarcoidosis, non-Hodgkin’s lymphoma, cirrhosis, and interstitial lung disease." (PMID 39768579, 2024). "When excluding 257 patients treated with ACE inhibitors from the analysis, sarcoidosis, non-Hodgkin’s lymphoma, cirrhosis, and interstitial lung disease still significantly increased the risk of elevated ACE levels." (PMID 39768579, 2024). "Among patients with sarcoidosis, ACE levels around the time of diagnosis were higher than ACE levels in remission." (PMID 39768579, 2024). "ACE, serum amyloid A, cytokines, chemokines, and microRNAs have been investigated as potential serum biomarkers in patients with sarcoidosis." (PMID 39852350, 2024). "ACE (angiotensin-converting enzyme) and lysozyme levels were also determined, ruling out sarcoidosis, and HLA-B (human leukocyte antigen) was determined, confirming the presence of HLA B*07 and HLA B*15." (PMID 38592169, 2024). "Specifically, patients with non-Hodgkin’s lymphoma, cirrhosis, interstitial lung disease, and sarcoidosis, all exhibited significantly elevated ACE levels." (PMID 39768579, 2024). "As multiple cranial nerves (seven, nine, and ten) were involved and he had a fever with a headache, we decided to perform CSF analysis and measure serum angiotensin-converting enzyme (ACE) levels (for sarcoidosis)." (PMID 39539892, 2024). "Serum angiotensin-converting enzyme (ACE) stands as the most studied biomarker in sarcoidosis, with earlier investigations suggesting elevated ACE levels in afflicted patients." (PMID 39365404, 2024). "Since sIL-2R is more sensitive than ACE for detecting sarcoidosis, it should be used to help differentiate ICI-induced SLR from other causes of inflammation and to monitor disease progress in patients undergoing ICI therapy." (PMID 39872587, 2024). "ANCA measurement aids in diagnosing vasculitis-related granulomas, whereas ACE and sIL-2R measurements help differentiate sarcoidosis from malignant lymphomas." (PMID 39184725, 2024). "Serum ACE level testing is regularly used as a supportive measure for the diagnosis and follow-up of sarcoidosis." (PMID 39768579, 2024). "Upon admission, the patient's blood tests showed elevated ACE levels, supporting the diagnosis of sarcoidosis." (PMID 39791085, 2024). "The results of a retrospective study on serum NSE level in sarcoidosis patients suggest that this marker has poor sensitivity on its own but shows improvement in combination with serum levels of ACE and sIL-2R (93.8%)." (PMID 38611622, 2024). "Despite ACE levels typically being elevated in sarcoidosis, they remained within the normal range for all three patients." (PMID 39717410, 2024). "Conversely, our patient’s ACE levels were unexpectedly low at 6 U/L (normal range: 16-85 U/L), deviating from the usual elevation in sarcoidosis." (PMID 39872587, 2024). "The epithelioid and giant cells that compose granuloma can express ACE, increasing the level of serum ACE in patients with sarcoidosis." (PMID 37868968, 2023).